S100A8 (S100 calcium binding protein A8)
Diseases named in the same sentence as S100A8 in open-access papers (continued):
Sharing a sentence is not in itself a finding about the gene and the disease.
atherosclerosis (continued). "A recent review on S100A8 and S100A9 involvement in cardiovascular biology and disease indicate that increased plasma levels of S100A8/A9 predict cardiovascular events in humans, and deletion of these proteins partly protects mice from atherosclerosis." (PMID 23209553, 2012). "These include a negative association between sRAGE levels and coronary artery disease in non-diabetic men, prediction of unstable plaque by S100A8/A9 levels in acute coronary syndromes, and of accelerated atherosclerosis by high levels of S100A12 in hemodialysis patients." (PMID 19284577, 2009). "M4 is thought to promote atherosclerosis, and due to its expression of metalloproteinase MMP7 and calcium-binding protein S100-A8, the presence of M4 is not conducive to plaque stability." (PMID 35637946, 2022). "Heterodimeric S100A8/S100A9, the form measued in this study, but not the monomeric forms, has been shown to increase detrimental effects caused by advanced end glycation products (AGEs) and may therefore play a role in triggering atherosclerosis in subjects associated with high levels of AGEs." (PMID 19823685, 2009).
chronic gastritis (59 papers, 2009 to 2025). Inflammation of the stomach that is chronic in nature. "Unsurprisingly, expression and distribution of S100A8/A9 in chronic appendicitis tissues with exacerbation (the positive control) were much alike those in chronic gastritis tissues." (PMID 22838504, 2012). "In addition, S100A9 and S100A8 proteins were detected in inflammatory cells in chronic gastritis." (PMID 22838504, 2012).
duodenal ulcer (54 papers, 2005 to 2025). An ulcer in the duodenal wall. "In our research, a significant high expression of S100A8/A9 in children with duodenal ulcer was found to be of good diagnostic value." (PMID 37450409, 2023). "Here, we identified that S100A8/A9 are highly expressed in the serum of children with duodenal ulcers, and this is of excellent diagnostic value." (PMID 37450409, 2023). "Our data indicated that S100A8/A9 were expressed with high level of diagnostic value in children with duodenal ulcer and S100A8/A9 is probably a diagnostic and therapeutic target for children with duodenal ulcers." (PMID 37450409, 2023). "Therefore, the elevated levels of S100A8/A9 in the serum of children with duodenal ulcers are probably caused by IL-17-induced reduction of neutrophils." (PMID 37450409, 2023). "Additionally, receiver operating characteristic curve (ROC) analysis demonstrated excellent diagnostic value of S100A8/A9 in children with duodenal ulcers." (PMID 37450409, 2023). "Hence, through investigating the potential molecular mechanisms, we identified the causative role and source of S100A8/A9 in children with duodenal ulcers." (PMID 37450409, 2023). "Therefore, S100A8/A9 may be newly found causative factors that were involved in children with duodenal ulcers." (PMID 37450409, 2023). "The results suggested that S100A8/A9 inhibitor Paquinimod can significantly reduce intestinal epithelial permeability in mice with duodenal ulcer." (PMID 37450409, 2023). "To clarify the role of S100A8/A9 in duodenal ulcer, we prepared mice with duodenal ulcer and then administered S100A8/A9 inhibitors-Paquinimod, and HE results showed that the degree of damage to the intestinal epithelium was significantly restored." (PMID 37450409, 2023). "In a word, we proposed S100A8/A9 as a novel biomarker for the clinical differential diagnosis of children with duodenal ulcer." (PMID 37450409, 2023). "In the current study, we examined the expression of S100A8/A9 in the serum of children with duodenal ulcers and also investigated the apoptotic effect of S100A8/A9 on intestinal epithelial cells." (PMID 37450409, 2023). "In conclusion, our present study indicated that S100A8/A9 are expressed highly in the serum of children with duodenal ulcers." (PMID 37450409, 2023). "Here, we identified a significant increase in the expression of S100A8/A9 in children with duodenal ulcers and it may contribute to the development of duodenal ulcer via promoting the apoptosis of intestinal epithelium." (PMID 37450409, 2023). "Therefore, we examined the expression of S100A8/A9 in neutrophils from children with duodenal ulcers after stimulation of IL-17A/F." (PMID 37450409, 2023). "Further studies suggest that S100A8/A9, derived from neutrophil, may deepen the development of duodenal ulcers by promoting apoptosis of intestinal epithelial cells." (PMID 37450409, 2023). "Thus, our research proves the value of S100A8/A9 in the diagnosis and treatment of children with duodenal ulcers." (PMID 37450409, 2023). "In addition, further study has shown that S100A8/A9, mainly produced by neutrophil, can enhance the apoptosis of intestinal epithelial cells and promote the growth in children with duodenal ulcers." (PMID 37450409, 2023). "However, this role of S100A8/A9 in children with duodenal ulcers is still unclear." (PMID 37450409, 2023). "In order to demonstrate whether S100A8/A9 were differently expressed in children with duodenal ulcer, the serum samples were collected in children with duodenal ulcer and people with non-ulcer, and the S100A8/A9 expression in children with duodenal ulcer was detected by ELISA." (PMID 37450409, 2023). "The effect of S100A8/A9 in children with duodenal ulcers is still unknown." (PMID 37450409, 2023).
duodenal ulcer (continued). "To identify the source of elevated the levels of S100A8 and S100A9 in children with duodenal ulcer, here, we analyzed the signaling pathways generated by S100A8 and S100A9, we found that IL-17 signaling pathway is involved in S100A8 and S100A9 production." (PMID 37450409, 2023).
melanoma (54 papers, 2008 to 2026). A malignant, usually aggressive tumor composed of atypical, neoplastic melanocytes. "Another group of genes and gene sets (e.g., AXL, HM angiogenesis, and HM inflammatory response) refers to the ST pattern associating with modules G and F. The gene S100A8 is reported to act as an early marker of melanoma development." (PMID 38785552, 2024). "•These findings underline the relevance of neutrophils and S100A8/A9 as drivers of melanoma progression." (PMID 39700646, 2024). "S100A8 overexpression is associated with tumorigenesis and poor differentiation in melanoma and prostate cancers, although the biological function of S100A8 in cancer is not clear." (PMID 36686780, 2022). "S100A8/A9 serum levels, neutrophil counts, and tumor-associated neutrophil infiltration represent promising biomarkers for predicting treatment response and clinical outcomes in melanoma patients receiving ICIs." (PMID 39700646, 2024). "S100A8+ melanoma cells emerged as the predominant malignant subpopulation in LN metastatic tumors (56.3% versus 34.7% in non-metastatic cases)." (PMID 42020397, 2026). "Our results reveal preferential SPP1+ signaling pathways, including autocrine amplification within secreted phosphoprotein (SPP) 1+ macrophages and their interactions with S100A8+ melanoma cells via the SPP1-CD44 axis." (PMID 42020397, 2026). "In vivo models showed that HRG suppresses S100A8/A9-mediated melanoma cell migration and invasion, particularly to the brain and lungs." (PMID 40332507, 2025). "Other S100 proteins with importance in melanoma include S100A8 and S100A9, which form heterodimers commonly known as calprotectin (also referred to as leucocyte L1 protein, calgranulin A/B, or the Myeloid-Related Protein (MRP8/14))." (PMID 40869349, 2025). "MCAM, which responds to S100A8/A9, promotes lung-specific metastasis in melanoma cells expressing this receptor." (PMID 40924339, 2025). "In conclusion, our results provide additional evidence that neutrophil activation followed by the secretion of NETs in combination with the release of S100A8/A9 constitute potential biomarkers for prediction of the prognosis in melanoma patients." (PMID 39700646, 2024). "The inflammation-associated S100A8 and S100A9 have been identified to attract melanoma cells and described as a critical factor for recruitment of myeloid-derived suppressor cells (MDSCs) and stimulation of their immunosuppressive functions in the TME." (PMID 39530091, 2024). "Even more upstream, the crucial early role of these alarmins was revealed in inducing pneumotropic metastasis of melanoma cells via their interaction with melanoma cell adhesion molecules in the framework of the S100A8/A9‐MCAM axis." (PMID 38775220, 2024). "Intriguingly, it was recently reported that elevated S100A8/A9 expression in the TME was correlated with resistance to PD-1 blockade in melanoma patients." (PMID 38378783, 2024). "A) The aim of our study was to provide evidence for S100A8/A9 and neutrophils as valuable prognostic and predictive biomarkers for tumor growth in melanoma." (PMID 39700646, 2024). "The increased expression of S100A8/A9 in primary melanoma has previously been attributed to melanoma-infiltrating immune cells whose abundance predicts shorter survival." (PMID 39201498, 2024). "In a study of patients with advanced melanoma revealed an exclusive and abundant expression of S100A8/A9 in cells of the TME, mainly granulocytes." (PMID 39530091, 2024). "Inflammatory cells, including Cd68+ macrophages and S100a8+ neutrophils were similarly present in the lungs at baseline and 6 h post melanoma injection, and were excluded from the analysis." (PMID 39627185, 2024). "Neutrophils and S100A8/A9 seem to define the prognosis of melanoma patients due to their impairment of T cell functions." (PMID 39700646, 2024).
melanoma (continued). "In this retrospective immuno-monitoring study, we sought to address the question if S100A8/A9 and neutrophils were reliable predictive biomarkers of clinical outcome in advanced melanoma patients." (PMID 39700646, 2024). "High numbers of S100A8/A9 expressing cells in melanomas would translate into elevated S100A8/A9 serum levels." (PMID 39530091, 2024). "In contrast, the spatial analysis of in situ melanoma detected S100A8 expression only in scattered immune cells within the dermis, suggesting a dominant role for keratinocyte S100A8 in the very early steps of melanomagenesis." (PMID 39201498, 2024). "In 43 metastatic unresected stage III/IV melanoma patients, elevated serum levels of S100A8/A9 and neutrophils before and during ICI treatment correlated with worse outcomes." (PMID 39700646, 2024). "Previous studies have demonstrated that SEC23A increases autophagy by promoting S100A8 autocrine in melanoma." (PMID 37670384, 2023). "Lung endothelial cells and alveolar macrophages were also shown to contribute to Mac1+-myeloid cell or BMDC recruitment to the lungs by releasing S100A8 in melanoma mouse model." (PMID 36607556, 2023). "In melanoma cells, activation of the S100A8/A9–MCAM–TPL2–ETV4–MMP25 axis promotes growth and lung metastasis in vivo." (PMID 37701037, 2023). "Ab45, an S100A8/A9 heterodimer-specific neutralizing antibody, efficiently blocks melanoma lung metastasis." (PMID 37701037, 2023). "It promotes the maintenance of MCAM protein at high levels and elevates the stability of MCAM by glycosylation, thus maintaining the responsiveness of MCAM to S100A8/A9 to increase melanoma cellular migration and invasion." (PMID 37701037, 2023). "The functional blocking of extracellular S100A8/A9 by the anti-S100A8/A9 neutralizing antibody Ab45, which we developed, efficiently prevents lung-directed melanoma metastasis even after a single injection." (PMID 36142212, 2022). "HRG prevents the binding of S100A8/A9 to the B16-BL6 melanoma cell surface via the formation of the S100A8/A9 complex." (PMID 36142212, 2022). "We previously reported that melanoma cells show lung-tropic metastasis owing to the abundant expression of S100A8/A9 in the lung." (PMID 36142212, 2022). "Further experiments showed that similar to melanoma EVs-treated DCs, the incubation of DCs with S100A8 and S100A9 proteins compromised their maturation in vitro." (PMID 34078376, 2021). "S100A8/A9 is a unique predictive guide for ipilimumab treatment in metastatic stage IV melanoma patients." (PMID 35003391, 2021). "Within the metal sequestration by the antimicrobial peptides pathway, the S100 family genes S100A7, S100A8, and S100A9 have been linked to tumor growth and metastasis in multiple cancers, including melanoma." (PMID 35008167, 2021). "Profiling of melanoma EV cargo revealed shared proteomic and RNA signatures including S100A8 and S100A9 protein cargo." (PMID 34078376, 2021). "Conversely, melanoma cells possessing several receptors that sense the S100A8/A9 ligand are attracted to an enriched S100A8/A9 lung environment." (PMID 33567747, 2021). "The activation of MAP3K8/ETV4 by S100A8/A9-CD146 binding finally results in lung tropic metastasis of melanoma." (PMID 32782280, 2020). "When monitoring stage IV melanoma patients during immunotherapy with ipilimumab, the heterodimer S100A8/S100A9 attracted attention, as high serum levels of it in early stages of treatment predicted worse response." (PMID 32722137, 2020). "In a more recent study, the role of S100A8/A9 as a lung attractant for melanoma metastases was confirmed." (PMID 33256110, 2020). "S100A8/A9 has also been proposed to be a prognostic marker for metastasis, as well as a predictor of survival and determinant of therapeutic response in melanoma patients." (PMID 33256110, 2020). "This study suggested that S100A8/A9 had the ability to attract melanoma cells to the lungs through the activation of RAGE." (PMID 33256110, 2020).
melanoma (continued). "In contrast to S100A8/A9, gene expression of the melanoma biomarker S100B was upregulated not only in melanoma metastases, but also in primary melanomas and in melanocytic nevi." (PMID 31806053, 2019). "On the other hand, distant melanoma cells catch the S100A8/A9 signal from the inflammatory lung through the MCAM sensor that exists on the melanoma cell surface, resulting in acceleration of lung-oriented metastasis of melanoma cells." (PMID 30899801, 2019). "The cDNA analysis revealed that S100A8/A9 gene expression was increased in metastases compared to primary melanomas." (PMID 31806053, 2019). "Immunofluorescence analysis of S100A8/A9 expression in tissue sections of primary melanomas revealed an exclusive and abundant expression of S100A8/A9 in cells of the TME, mainly granulocytes, whereas S100B expression was restricted to melanoma cells." (PMID 31806053, 2019). "S100A8/A9 protein expression in melanoma tissue was analyzed in three independent tissue microarrays (TMA)." (PMID 31806053, 2019). "We showed that measurement of serum S100A8/A9 provides prognostic value for melanoma patients with metastatic stages III and IV." (PMID 31806053, 2019). "Altogether, by presenting clinical data, this study strengthens the mechanistic impact of S100A8/A9 on metastasis and progression in melanoma patients." (PMID 31806053, 2019). "Profiling of melanoma EV cargo identified shared proteomic and RNA signatures including S100A8 and S100A9 protein cargo, which in vitro compromised DC maturation similar to melanoma EVs." (PMID 28424693, 2017). "Taken together, these data suggest melanoma EV cargo, including established chronic inflammatory mediators S100A8 and S100A9 have the capacity to drive EV inhibitory effects on DC maturation." (PMID 28424693, 2017). "Furthermore, RAGE and MCAM have also been reported to bind to S100A8/A9 protein heterodimers, mediating signaling in malignant melanoma." (PMID 41294858, 2025). "These receptors may function cooperatively in melanoma cells to facilitate S100A8/A9-driven organ-specific metastasis." (PMID 40924339, 2025). "In melanoma cells, S100A8/A9 also induces pro-inflammatory factors and MMPs." (PMID 39201498, 2024). "In addition, S100A8/A9 promotes melanoma growth and cell motility, and it functions as a strong soil signal in pre-metastatic organs by attracting melanoma cells through their S100A8/A9 sensors." (PMID 39201498, 2024). "Interestingly, melanoma-secreted exosomes were shown to induce a strong expression of S100A8 and S100A9 in human primary keratinocytes, but the exosomal components triggering this effect were not identified." (PMID 39201498, 2024). "In melanoma, S100A8/A9 expression in adjacent keratinocyte, which is significantly associated with an invasive melanoma tumor type, was proposed as a valuable marker complementary to melanoma-specific antigens for the differential diagnosis of early melanoma and nevi." (PMID 39201498, 2024). "HRG also inhibited the S100A8/A9-induced migration and invasion of A375 melanoma cells." (PMID 36142212, 2022). "The local and systemic balance between HRG and S100A8/A9 may regulate the migration, invasion, and metastasis of melanoma and could be a determinant of cancer pathogenesis leading to an aggressive phenotype." (PMID 36142212, 2022). "For example, TLR4, RAGE, and EMMPRIN were reported to be expressed in metastatic melanoma cells, and the EMMPRIN-mediated stimulation of melanoma cells with the extracellular S100A8/A9 secreted from the lung strongly facilitated the remote metastasis of melanoma cells to the lung." (PMID 36142212, 2022). "For instance, melanoma cells from distant organs induce S100A8/A9 expression in the lung." (PMID 33567747, 2021). "Thus, the association of PRAME, CXCL9, CXCL10, S100A7, S100A8, and S100A9 with melanoma progression is supported by prior studies and commercially available clinical tests." (PMID 35008167, 2021).